INS (insulin)
Diseases named in the same sentence as INS in open-access papers (continued):
Sharing a sentence is not in itself a finding about the gene and the disease.
Obesity (continued). "In already obese animals, the impact of the protein source on obesity varies depending on energy intake and macronutrient composition, whereas glucose tolerance and insulin sensitivity in general follow the differences detected in obesity development." (PMID 31126082, 2019). "The effect of obesity on insulin and IGF-1-mediated responses in resistance vessels has been unclear." (PMID 30295509, 2019). "Fatty acids and TNF-α have been shown to induce M1 polarization in obesity but also glucose, insulin, and obesity-induced hypoxia trigger macrophages toward a pro-inflammatory phenotype." (PMID 31333642, 2019). "SLC35B4 was cloned and firstly reported in 200535, but in the past one decade, there was almost no any report on its biological functions except few studies demonstrated that it is involved in the regulation of obesity, insulin resistance and gluconeogenesis." (PMID 31175271, 2019). "Osteopontin acts as a mediator of obesity-related hepatic alterations including steatosis, inflammation, insulin resistance, and excess gluconeogenesis." (PMID 31736870, 2019). "During obesity, there is an imbalance between insulin‐stimulated leptin‐induced anorexigenic and orexigenic signaling." (PMID 31660128, 2019). "These include well-studied processes such as obesity, fat distribution, islet development and function, and insulin sensitivity, although there are likely to be others that are, as yet, less clearly described." (PMID 31322649, 2019). "With POMC‐mediated leptin and insulin function playing a major role in the pathological development of obesity and MeS, the methylation status of POMC thus represents a pivotal therapeutic target." (PMID 31660128, 2019). "Apelin is a recently discovered adipokine that has been reported to improve sugar intake and insulin sensitivity, to promote energy consumption, and to reduce blood pressure, while also being important in obesity-related metabolic disease." (PMID 30696454, 2019). "The Nrf2 activity suppressed the hypothalamic oxidative stress, resulting in the improvement of the resistance of insulin and leptin related to obesity." (PMID 31817423, 2019). "Higher levels of Fasn mRNA and FAS protein have been described in obesity, in visceral fat accumulation, and in enlarged insulin-resistant adipocytes." (PMID 31133986, 2019). "TCRδ −/− mice, which lack γδ T cells, were more insulin sensitive compared to wild-type mice in response to HFD, indicating γδ T cells promote obesity-associated inflammation." (PMID 31379820, 2019). "The relation between obesity and cancer is complicated and involves alterations in insulin metabolism, response to inflammation and alterations in estradiol metabolism." (PMID 31174495, 2019). "PON2-def mice had increased fasting insulin levels and impaired glucose tolerance after diet-induced obesity." (PMID 30641857, 2019). "Adiponectin has been largely studied in obesity and related diseases, and well-known are its insulin-sensitizing, anti-atherogenic, and anti-inflammatory properties." (PMID 31547312, 2019). "Greater GWG in early pregnancy may reduce maternal insulin sensitivity and glucose tolerance which could expose the fetus to an increased glucose supply and further alter the development of fat cells in fetus, resulting in increased risk for obesity throughout the lifecourse." (PMID 30695989, 2019). "In fact, carnitine insufficiency is a common feature of insulin-resistant states such as advanced age and diet-induced obesity in rodents." (PMID 31349613, 2019). "Data are limited to mouse models, which have demonstrated certain novel clock-improving molecules to have benefits, with decrease in obesity and hyperglycaemia and improvement in insulin sensitivity." (PMID 31766545, 2019). "Recent studies reported that adipose overexpression of ATGL attenuated diet-induced obesity and improved insulin sensitivity." (PMID 31147543, 2019).
Obesity (continued). "While it has been clearly demonstrated that hyperinsulinaemia in obesity leads to significantly reduced GH secretion, which affects insulin's ability to maintain normal glucose homeostasis." (PMID 31130916, 2019). "Both fiber and acetate decrease gut dysbiosis, measured by F/B ratio, and increase the prevalence of Bacteroides acidifaciens, a bacterium involved in the prevention of obesity and improvement of insulin sensitivity in mice." (PMID 31091761, 2019). "The CXCL12 gene is involved in macrophage recruitment, and it is a factor required for obesity-induced adipose tissue inflammation and systemic insulin resistance." (PMID 30764545, 2019). "They found that 14 miRNAs were significantly (p < 0.05) dysregulated in fasting plasma of children with obesity and IR compared to children with obesity and insulin sensitivity." (PMID 31783635, 2019). "Given this insulin-sensitizing property, apelin has become a promising therapeutic target for treating obesity and diabetes." (PMID 31718027, 2019). "In that report, the authors concluded that SDF-1 was required for the establishment of obesity-induced adipose tissue inflammation and systemic insulin resistance." (PMID 30909581, 2019). "PAI‐1 levels increase with age in mice and humans and are increased by obesity, insulin resistance, and inflammation (Alessi & Juhan‐Vague, 2006; Khan, 2017)." (PMID 30916479, 2019). "Park2 KO mice are protected from diet‐induced obesity and hepatic insulin sensitivity is improved in high‐fat diet (HFD)‐fed Park2 KO mice even under body weight‐matched conditions." (PMID 31724300, 2019). "Findings from several studies have also confirmed that some children with obesity, and their relatives, display a low insulin secretion capacity to maintain euglycemia in insulin-resistant states." (PMID 31920976, 2019). "High secretion of tumor necrosis factor-alpha (TNF-α), interleukin-6 (IL-6), monocyte chemoattractant protein-1 (MCP-1), and additional products of macrophages by adipose tissue with low sensitivity to insulin has also been detected in obesity." (PMID 30678306, 2019). "In order to better understand the mechanism of Rb2 in ameliorating obesity and improving insulin sensitivity, we systematically analyzed the actions of Rb2 on energy expenditure using comprehensive lab animal monitoring system (CLAMS)." (PMID 30930854, 2019). "In conclusion, we showed that daily use of KI composition is efficient in decreasing blood sugar and blood fat, improving the insulin production in islets, or decreasing obesity in STZ-induced diabetic rats or in db/db mice." (PMID 31687407, 2019). "Independently from insulin and obesity, the existence of a correlation between Chemerin and PCOS has repeatedly been evoked." (PMID 31505789, 2019). "A protein in adipose tissue (composed of fat cells) helps protect against inflammation and the development of resistance to insulin that develops in obesity and can lead to type 2 diabetes." (PMID 31113929, 2019). "Typically, during obesity, fasting glucose levels are increased, which prompts β-cells to increase their mass and insulin secretion to maintain euglycemia." (PMID 31300714, 2019). "It exerts anti-inflammatory, anti-obesity, anti-diabetic properties, and has beneficial effects on exercise-induced insulin-sensitization." (PMID 31208019, 2019). "In diet-induced obesity the hypothalamic leptin and insulin signaling is largely changed, and these changes are the result of hormonal dysregulations and metabolic dysfunctions." (PMID 30870482, 2019). "In rodents, the administration of catestatin decreases hypertension, cardiac contractility, obesity, atherosclerosis, and inflammation, and it improves insulin sensitivity." (PMID 31588572, 2019). "In summary, the serological and hormonal profile of obese MTB/TAN mice suggests the adipokine and insulin/IGF-1 signaling pathways as potential mediators of a relationship between obesity and breast cancer recurrence in this model." (PMID 30867005, 2019).
Obesity (continued). "Similar to neuronal-specific PTP1B deletion, POMC-specific deletion of PTP1B rendered mice resistant to diet-induced obesity, increased energy expenditure, enhanced leptin and insulin sensitivity and improved glucose homeostasis." (PMID 31319588, 2019). "The biological relation between obesity and cancer is complex, and involves alterations in insulin metabolism, inflammatory response and sex steroid metabolism." (PMID 31174495, 2019). "Mice with deletion of Fms-like tyrosine kinase 3 ligand (Flt3L), that lack DCs, revealed reduced macrophage number in the AT and liver as well as improved insulin sensitivity in diet-induced obesity." (PMID 32063863, 2019). "The abundant insulin would then act through other signaling pathways that are less affected by DM or obesity (e.g., the Ras/MAPK pathway)." (PMID 30962800, 2019). "To examine the temporal effect of obesity on insulin and IGF-1-mediated phosphorylation of the key signalling kinase Akt, we performed in vivo administration of either insulin or IGF-1 to HF and LF fed mice after 2, 5 and 16 weeks." (PMID 30295509, 2019). "Mitochondria are clearly considered to be main contributors to oxidative stress in obesity induced by chronic over-nutrition, with subsequent reduced insulin sensitivity or IR." (PMID 31861591, 2019). "As it is influenced by inflammation, the reduction in the levels of SOCS3 has been reported to be a protective factor that acts to prevent obesity-induced insulin sensitivity." (PMID 31060494, 2019). "In contrast to the results observed after LepR reactivation in adult mice, LepR reactivation before the onset of obesity completely normalized the glucose tolerance and insulin sensitivity in both male and female Ubi-LepRNull mice." (PMID 30694175, 2019). "Obesity is a risk factor related to EC due to PI3K pathway and insulin signaling mutations, which occur in most endometrioid adenocarcinomas." (PMID 34322276, 2019). "On the other hand, the effect of TNFa on obesity increased the release of fatty acid by adipocytes, reduced adiponectin synthesis, and impaired insulin signalling." (PMID 31093012, 2019). "And after limiting energy intake for 6 weeks, patients with a high abundance of A. muciniphila at baseline had significantly improved insulin sensitivity and other obesity‐related clinical indicators." (PMID 31006995, 2019). "PTP1B-deficient mice showed improved insulin sensitivity and resistance to HFD-induced obesity, while on the other hand, TC-PTP-deficient mice died in early life due to increased overall inflammation and severe anemia." (PMID 31319588, 2019). "Consistently, injection of recombinant chemerin aggravated glucose intolerance, reduced serum insulin levels, and impeded tissue glucose uptake in mouse models of obesity and diabetes." (PMID 31208019, 2019). "The proapoptotic state found in obesity is correlated with insulin signaling, suggesting it can play a role in insulin resistance." (PMID 31092860, 2019). "Obesity contributes to the initiation of chronic inflammation, and inflammation inhibits the insulin signaling activity in hepatocytes and adipocytes." (PMID 31281547, 2019). "This suggests the effect of obesity on insulin BBB transport is mediated by changes in circulating factors, one of which is the triglyceride triolein." (PMID 31213970, 2019). "Increased insulin, amino acids and pro-inflammatory cytokines due to chronic overnutrition in the context of obesity activate mTORC1 that mediates feedback inhibition to PI3K/AKT pathway." (PMID 31244863, 2019). "On the other hand, diet-induced obesity promotes an insulin-dependent increase in PI3K signaling in the VMN." (PMID 30755252, 2019). "Thereby, IL-6 contributes to the adaptation of β-cell function to the increased insulin demand in physiology and obesity." (PMID 30989320, 2019).
Obesity (continued). "This study sought to compare the effects of a 12‐week ECC vs CON cycling training on body composition, aerobic capacities, quadriceps strength, insulin resistance, and blood lipid profile in adolescents with obesity." (PMID 30222208, 2019). "Night work-related disruptions of the biological clock are likely to result in obesity, impaired insulin secretion, and aberrant glucose homeostasis." (PMID 30922333, 2019). "Here, using yeast two-hybrid screening, we show that Zfp238 is a Foxo1 co-repressor and that adipose-tissue-specific ablation of Zfp238 (Adipo-Zfp238KO) in mice leads to obesity, decreased energy expenditure, and insulin resistance under normal chow diet." (PMID 30677742, 2019). "This review highlights changes in miRNAs involved with insulin sensitivity, glucose tolerance, and lipid metabolism both in obesity and CRC." (PMID 31207998, 2019). "In obesity, vitamin D affects insulin secretion, tissue sensitivity to insulin, and systemic inflammation." (PMID 30881343, 2019). "Another Lactobacillus gasseri strain, BNR17 with promising anti-obesity effects reduced body weight, white adipose tissue weight, serum leptin, and insulin levels in mice fed a high carbohydrate diet when administered twice daily for 12 weeks." (PMID 30678355, 2019). "Elevated blood glucose and impaired insulin sensitivity are hallmarks of metabolic syndrome and are thus a chief concern of individuals with diet-induced obesity." (PMID 30736418, 2019). "Diet‐induced DNA methylation changes occurring within ARC genes, particularly POMC and INS‐R, which prevents an appropriate response to leptin and insulin, thereby affecting energy homeostasis, subsequently leading to the development of obesity and MeS." (PMID 31660128, 2019). "In one of those early studies, it was shown that women with predominantly upper segment obesity and a significantly higher plasma glucose and insulin levels compared to lower segment." (PMID 31116758, 2019). "The exception is the BPD, after which an improvement in both, hepatic and peripheral insulin sensitivity since early stages and to a greater extent compared to weight-matched controls undergoing other obesity interventions can be observed." (PMID 31608010, 2019). "Supportive of the key role of peripheral inflammation in obesity, obese myeloid-specific IKKβ or JNK deficient mice exhibit improved systemic insulin sensitivity." (PMID 31497027, 2019). "Confounders included for adjustment were age, sex, and comorbidities (hypertension, hyperlipidemia, coronary artery disease, obesity, diabetic retinopathy, chronic kidney disease, and insulin treatment)." (PMID 31781371, 2019). "The present study was designed to determine the effect of herring milt protein hydrolysate (HPH) on insulin function and glucose metabolism in a mouse model of diet-induced obesity." (PMID 31382619, 2019). "Consistent with previous studies, our univariate analysis showed that age, male, oral antidiabetic agents, insulin use, current smoking, current drinking, obesity, and increased TG were significantly different when considering GGT levels." (PMID 30984786, 2019). "In the same study, 14-day treatment with etanercept, a TNF-α blocker, similarly improved islet insulin secretion in the obesity-single-low dose streptozotocin model." (PMID 30989320, 2019). "It was found that an aberrant response to insulin is developed in the liver in little as 3 days of HFD feeding before the development of overt obesity." (PMID 31847157, 2019). "The state of insulin and glucose metabolism are pertinent to design and interpretation of studies of DA signaling in obesity." (PMID 30849082, 2019). "In unhealthy obesity, fat mobilization from adipocytes is impaired, and insulin is unable to suppress lipolysis." (PMID 31085992, 2019). "Correlational analysis was also used to investigate potential relationships between the Nur77 and NOR1 response to insulin and markers of obesity and metabolic health." (PMID 30912283, 2019).
Obesity (continued). "Increased insulin secretion results in obesity, which, with time and Western diet, progress into metabolic syndrome." (PMID 31024034, 2019). "Global knockdown of the Let-7 family with an anti-miR was apt to anticipate and treat impaired glucose tolerance in mice with diet-induced obesity, at least in part by improving insulin sensitivity in liver and muscle." (PMID 31861591, 2019). "The Nrf2 activity then suppressed the hypothalamic oxidative stress, subsequently improving the resistance of insulin and leptin related to obesity." (PMID 31817423, 2019). "Obesity-related inflammation of metabolic tissues, including liver and adipose tissue, are key elements in the development of metabolic inflammation and insulin resistance, but many of the contributing mechanisms remain ambiguous." (PMID 31552019, 2019). "Furthermore, an increased P. mirabilis abundance was observed in rats that underwent a high-fat diet, also being significantly correlated with triglyceride levels, and leptin and insulin concentration, indicating that this bacterium may be associated with low-grade inflammation linked to obesity." (PMID 30641996, 2019). "We have previously shown that, in children with obesity, the presence of an adverse metabolic phenotype is independently affected by both the degree of obesity and by a reduction of whole-body insulin sensitivity." (PMID 30637483, 2019). "The hypothalamic IKKβ/NF-κB signaling pathway is involved in the inflammatory response, and contributes to the pathogenesis of obesity by inducing an insulin and leptin resistance through inflammation of the hypothalamic cells." (PMID 30886629, 2019). "Both obesity per se and low insulin sensitivity are independent determinants of the adverse metabolic phenotype characteristic of the metabolic syndrome." (PMID 31474943, 2019). "Given the role of PI3Kγ in inflammation, and the role of inflammation in obesity-induced insulin resistance, it is well understandable that PI3Kγ affect insulin signaling through the immune system." (PMID 31480354, 2019). "This study aimed to evaluate the capacity of Sambucus nigra fruit extract to mitigate obesity-related metabolic complications through the carbohydrate and lipid metabolism regulation, glucose uptake improvement, and insulin sensitivity controlling." (PMID 31398785, 2019). "In conclusion, our data demonstrate that insulin sensitivity of the maternal white adipose is a key factor mediating the reduced glucose tolerance of the mother due to diet‐induced obesity." (PMID 31466137, 2019). "In contrast, obesity and/or diabetes are related to ROS overproduction, which in turn induces inflammation, thereby blunting insulin signaling." (PMID 30875909, 2019). "As the leptin concentration increases, appetite and adipogenesis both increase, whereas the increase in adiponectin concentration increases insulin sensitivity and lipolysis, thereby improving obesity." (PMID 31137884, 2019). "In obesity, a paracrine loop between adipocytes and macrophages augments chronic inflammation of adipose tissue, thereby inducing systemic insulin resistance and ectopic lipid accumulation." (PMID 30914769, 2019). "Several miRNAs are involved in the regulation of glycemia and secretion of insulin being up- or down-regulated by obesity, such as miR-30a, miR-25 and miR-92a, which are involved in transcription, differentiation, and synthesis of insulin." (PMID 31817583, 2019). "Less information is directly available on NET generation, even if it is known that both insulin and hyperglycaemia, which are hallmarks of severe obesity have been suggested to facilitate neutrophil activation." (PMID 31604985, 2019). "For example, SCFAs generally exert health-promoting effects, including suppressing inflammatory responses, regulating energy homoeostasis, enhancing insulin sensitivity, promoting metabolic benefits, and protecting against obesity." (PMID 31164448, 2019).